RBM10 (RNA binding motif protein 10)
Diseases named in the same sentence as RBM10 in open-access papers (continued):
Sharing a sentence is not in itself a finding about the gene and the disease.
tumor (continued). "However, in OV, PAAD, and SKCM, the RBM10 expression decreased with increasing tumor grades." (PMID 39282149, 2022). "However, the potential molecular mechanism of RBM10 mutation affecting the clinical prognosis of tumor patients has not been clarified yet, and further exploration is needed in the future." (PMID 39282149, 2022). "RBM10 can regulate mRNA alternative splicing and may act as a tumor suppressor in some contexts." (PMID 35579943, 2022). "However, recent studies have also reported that RBM10 also plays a role in promoting tumor growth through an unknown mechanism." (PMID 33718153, 2021). "In our study, LUAD samples with RBM10 PTVs showed dramatically lower RBM10 expression levels compared to both LUAD samples lacking RBM10 mutations or CNAs and tumor-matched normal tissues, the former of which displayed higher RBM10 expression levels relative to the latter." (PMID 28091594, 2017). "From the expression level, four RBPs (RBM10, PUM2, QKI2, and TARBP2) were downregulated in tumor tissues compared with normal tissues, while other identified RBPs were consistently upregulated in OS cells." (PMID 37426488, 2023). "RNA-binding motif protein 10 (RBM10), one of the members of the RNA-binding protein (RBP) family, has a tumor suppressor role in multiple cancers." (PMID 34975322, 2022). "RBM10 can also reduce the activation of RAP1A and decrease phospho‐AKT and phospho‐CREB to inhibit tumor proliferation." (PMID 33718153, 2021). "Altogether, these studies highly suggest that RBM10, similar to RBM5 and RBM6, possesses a tumor suppressive function via different mechanisms." (PMID 32947864, 2020). "Age did not impact the effects of inactivation of Stag2, Setd2, Cdkn2c and Rbm10 in either context, further suggesting that age interacts with specific tumor suppressor pathways as opposed to generically weakening the effects of driver mutations." (PMID 41188600, 2025). "Notably, RNA-binding motif protein 10 (RBM10), an RBP family member, exhibits tumor–suppressive properties in multiple cancers." (PMID 40271197, 2025). "Remarkably, RBM10-I316F not only failed to suppress the tumor growth but also appeared to significantly promote the growth of xenograft tumors." (PMID 38032932, 2023). "Unfortunately, there is no relevant study on the molecular mechanism of RBM10 methylation affecting tumor prognosis." (PMID 39282149, 2022). "PALB2 and RBM10 are involved in DNA repair; their involvement in the tumor process is not surprising." (PMID 34284772, 2021). "Moreover, RBM5 and RBM10 have 401 common targets, indicating that RBM5 and RBM10 work together during the progression of tumor development." (PMID 33718153, 2021). "Previous studies have shown tumor-suppressor properties for both RBM5 and RBM10." (PMID 28662214, 2017). "To examine how these mutations affect gene expression, we compared RBM10 mRNA levels in LUAD samples harboring different types of RBM10 mutations with LUAD samples lacking RBM10 mutations and samples from tumor-adjacent normal tissues." (PMID 28091594, 2017). "Our results provide evidence that RBM10 expression, in RBM5-null tumors, may contribute to tumor growth and metastasis." (PMID 28662214, 2017).
tumor (continued). "Interestingly, we observed that 92% of RBM10 alterations present in our EGFR-mutant tumor data set did not co-occur with a known EGFR TKI resistance–associated mutation such as EGFR T790M or C797S or MET gene amplification." (PMID 35579943, 2022). "RBM10 deficiency does not modulate the oncoprotein target itself (here, mutant EGFR), but instead functions via the differential regulation of the apoptotic machinery in tumor cells." (PMID 35579943, 2022). "In this study, we found that the RBM10 expression was negatively correlated with B cells, CD8+ T cells, neutrophils, macrophages, and DC cell infiltration levels in most tumor types, indicating that RBM10 was likely to affect tumor development and prognosis by impacting the tumor microenvironment." (PMID 39282149, 2022). "Since RBM10 would no longer influence cellular processes, RBM5 could exercise its RBM10v2-independent tumor-suppressor properties." (PMID 28662214, 2017).
cancer (48 papers, 2013 to 2025). A tumor composed of atypical neoplastic, often pleomorphic cells that invade other tissues. "Dysregulation of RBM10 has been implicated in several of diseases, notably cancer such as lung, breast, and ovarian, besides neurological disorders and specific genetic syndromes." (PMID 40941029, 2025). "In conclusion, the loss of RBM10 in cancer cells leads to extensive disruption in the splicing of mRNAs related to cytoskeletal and extracellular matrix (ECM) components." (PMID 39874138, 2025). "RBM10 exhibits a high mutation rate in various cancers, including LUAD, colon cancer, and liver cancer." (PMID 40069781, 2025). "By enabling greater cell motility, promoting ECM remodeling and potentially aiding immune evasion, RBM10 loss supports cancer cell dissemination and colonization of new tissues." (PMID 39874138, 2025). "RBM10 is an RNA-binding protein located in the nucleus that plays a crucial role in RNA splicing and is implicated in several human diseases, including cancer." (PMID 37775701, 2023). "RBM10 mutations are capable of changing the microenvironment of tumors and promoting their progression, rendering it a potential target for personalized cancer treatment." (PMID 36335386, 2022). "The expression of RBM10 was negatively linked with ImmuneScore of 22 cancers, StromalScore of 17 cancers, and ESTIMATEScore of 22 cancers but positively linked with these three scores in UVM." (PMID 39282149, 2022). "In our research, RBM10 gene alternations were mainly “mutations” in most cancers, and the mutation frequency was the highest in LUAD, UCEC, and BLCA, which was consistent with the previous results." (PMID 39282149, 2022). "In conclusion, RBM10 mutations can be used as an independent prognostic factor for a variety of prominent cancers affecting patient survival and quality of life." (PMID 33718153, 2021). "In the future, we need to study what causes these two opposing effects of RBM10 on cancer regulation and development." (PMID 33718153, 2021). "SF1 is recurrently mutated across cancers in a mutually exclusive fashion (i.e., indicating its analogous functionality) to RBM10, a gene found to drive aberrant splicing events in cancer." (PMID 32711844, 2020). "Accordingly, RBM10 is revealed as a cancer-associated gene and listed in the Catalog of Somatic Mutations in Cancer (COSMIC) database." (PMID 32947864, 2020). "Understanding the mechanisms that regulate RBM10 expression and function would help to predict the impact of RBM10 mutation on cellular processes and thus potential patient outcomes in a disease such as cancer." (PMID 29274279, 2018). "The methods we employed should be useful for the functional characterization of additional RBM10 mutations and mutations in other cancer-associated splicing regulators." (PMID 28091594, 2017). "Thirdly, our work confirms that changes in RBM10 expression levels impact both cancer-associated and non-cancer-associated genes." (PMID 28728573, 2017). "Firstly, our work demonstrates that downregulation of RBM10 expression correlates with substantial changes in the alternative splicing of a number of pre-mRNAs associated with cancer." (PMID 28728573, 2017). "RBM10 had networks with 8 out of 1884 (0.4%) differentially expressed cancer-associated genes on 5q." (PMID 29156680, 2017). "Interestingly, we also found that the ICP genes significantly associated with RBM10 expression were different in different cancers." (PMID 39282149, 2022). "RBM5, RBM6, and RBM10 are commonly deleted, mutated, and/or under-expressed or overexpressed genes in many cancers; however, they have different roles in in vitro colony formation assays, partially due to their antagonistic regulation of NUMB alternative splicing." (PMID 36006412, 2022).
cancer (continued). "Data reveal the aberrant RBM10 expression in most tumors, and its expression is positively or negatively linked with the clinical prognosis of various cancers, depending on the different types and subtypes of cancers." (PMID 39282149, 2022). "Loss of function of RBM10 mutations is common in many cancer patients." (PMID 33718153, 2021). "RBM10 is an RNA-binding protein frequently deleted or mutated in cancer cells." (PMID 32947864, 2020). "The high incidence of RBM10 mutations in cancer suggests that they might contribute to pathogenesis of this disease." (PMID 28379442, 2017). "Knockdown of RBM10 was, therefore, associated with changed ASEs in cancer cell lines." (PMID 28728573, 2017). "However, a previous study found that the RBM10 mutations could lead to a poor prognosis of metastatic diseases and a high risk of cancer recurrence." (PMID 33718153, 2021). "Moreover, since our findings showed amplification of chromosome 5 we built RBMX and RBM10 gene regulatory network specifically with the cancer-associated genes located on chromosome 5p (33 genes) and 5q (68 genes) in BRAFV600E-PTC compared to BRAFWT-PTC TCGA samples." (PMID 29156680, 2017). "As the complexities of RBM10’s role in metastasis are unraveled, new therapeutic opportunities are likely to emerge to help limit cancer spread and improve patient outcomes." (PMID 39874138, 2025). "RBM10 (RNA-binding motif protein 10) is an RNA splicing factor known to influence cancer progression by regulating splicing events in specific genes." (PMID 39874138, 2025). "The protein expression levels of RBM10 were consistent with RT-qPCR analysis of 14 pairs of patient cancer and para-cancerous tissues, showing that RBM10 mRNA levels in PAAD tissues were lower than in para-cancerous tissues (P < 0.01)." (PMID 40740233, 2025). "We evaluated 6 splicing factor mutations commonly observed in cancer, including hotspot mutations in SF3B1K700E, U2AF1S34F, and CRISPR-engineered loss of function in FUBP1, RBM5, RBM10, and ZRSR2." (PMID 41279721, 2025). "For example, while AS-NMD is used for the inhibition of RBM10 to RBM5, RBM5 also controls the expression of RBM10 splicing variants in turn through AS-NMD to reduce the action of cancer promotion." (PMID 40275278, 2025). "Our data further imply a close interaction between RBM10 expression and the PD-1 pathway in cancer development." (PMID 40740233, 2025). "Targeting the mechanisms downstream of RBM10 loss, particularly the pathways governing cytoskeletal and ECM dynamics, presents a promising direction for reducing metastasis in aggressive cancers." (PMID 39874138, 2025). "We found that overexpression of RBM10 markedly inhibits c-Myc expression in cancer cells by destabilizing c-Myc protein via ubiquitin-mediated proteolysis." (PMID 38032932, 2023). "Taken together, these results demonstrate that the cancer-derived mutant RBM10-I316F loses its ability to suppress c-Myc expression and activity." (PMID 38032932, 2023). "These reversible effects were evident even when cancer cells were cultured under serum stimulation conditions, indicating that serum-responsive c-Myc activation is also inhibited by RBM10." (PMID 38032932, 2023). "Despite the possible advantages of RBM10 mutations in the early stage of cancer initiation, they may have a deleterious effect in later stages, i.e., when the cancer spreads and is attacked by immune cells (see the section below on transcriptional changes during cancer development)." (PMID 38102134, 2023). "RBM10 is significantly overexpressed in many malignant tumors, and it inhibits the proliferation and clonal formation ability of A549 cells and enhances the sensitivity of A549 cells to the chemotherapy drug paclitaxel by inducing apoptosis." (PMID 37509501, 2023). "Previous studies showed that RBM10 possesses anticancer activity by regulating alternative splicing of several cancer-relevant genes." (PMID 38032932, 2023).
cancer (continued). "The immunohistochemistry analysis showed that the cell nuclei of the carcinoma tissues were significantly enlarged and deeply stained, and RBM10 was expressed in the nucleus and cytoplasm." (PMID 37509501, 2023). "In here, we provide the first comprehensive assessment of the prognostic value and immunological function of RBM10 in human pan-cancer utilizing multiple public databases." (PMID 39282149, 2022). "The major biological functions of RBM10 include regulation of mRNA stabilization, alternative splicing, nuclear output, and translation 9-11; yet, the exact role of RBM10 in cancer progression remains controversial." (PMID 34975322, 2022). "In here, the RBM10 expression was found to be negatively correlated with StromalScore, ImmuneScore, and ESTIMATEScore in a variety of cancers, especially in GBM, LUSC, and SARC." (PMID 39282149, 2022). "Due to the heterogeneity of gene expression and function, the specific role and molecular mechanisms of RBM10 in various human cancers require further exploration." (PMID 39282149, 2022). "Here, for the first time, we found a negative correlation between RBM10 mRNA level and DNA methylation level based on pan-cancer, indicating a potential regulatory role of DNA methylation in RBM10." (PMID 39282149, 2022). "Then, the top 50 genes significantly related to the RBM10 expression in the TCGA pan-cancer dataset were obtained using GEPIA2." (PMID 39282149, 2022). "In this review, we provide a new perspective on the reasons for these opposing effects on cancer biology, molecular mechanisms, research progress, and clinical value of RBM10." (PMID 33718153, 2021). "By calibrating the expression of RBM10, it is theoretically possible to alter the development of cancer, and thus offer new therapeutic alternatives." (PMID 33718153, 2021). "Overexpression of RBM10 inhibits cancer cell proliferation, migration and mitochondrial respiration and promotes apoptosis." (PMID 34804951, 2021). "Supporting this notion, the ability of mutant RBM10 to bind to MDM2 is reduced as measured by co-IP-IB analysis in cancer cells." (PMID 32947864, 2020). "We used siRNAs to inhibit RBM10 expression in two ovarian, two breast and one prostate cancer cell line(s), as well as one non-cancer cell line." (PMID 28728573, 2017). "Re-expression of RBM10, in a stable RBM10 KD cancer cell line, correlated with a reversion of the KD effect, demonstrating specificity." (PMID 28728573, 2017). "Our previous study revealed that RBM10 promotes exon skipping in its target genes, including the cancer genes NUMB and CREBBP26." (PMID 28091594, 2017). "RBM10 is an RNA-binding protein implicated in talipes equinovarus, atrial septal defect, Robin sequence, and persistent left superior vena cava (TARP) syndrome and various cancer types." (PMID 40742131, 2025). "Notably, in the Chinese population, RBM10 mutations are present in about 8% of all LUAD cases, making it the fourth most common mutated gene in this cancer type." (PMID 40069781, 2025). "Our findings also suggest that the cancer-derived RBM10-I316F could promote cancer cell proliferation and survival by potentially suppressing the activity of its wild-type counterpart." (PMID 38032932, 2023).